ASPM (assembly factor for spindle microtubules)
Diseases named in the same sentence as ASPM in open-access papers (continued):
Sharing a sentence is not in itself a finding about the gene and the disease.
lung carcinoma (14 papers, 2015 to 2025). "ASPM expression levels were significantly elevated in lung cancer tissues and were closely associated with LUAD progression." (PMID 35741714, 2022). "The aim of this study was to investigate the relationship between the expression of abnormal spindle-like microcephaly-associated protein (ASPM) in lung adenocarcinoma and the development and prognosis in lung cancer." (PMID 31948535, 2020). "The results of the IHC assay revealed that, compared with paracancerous tissues, lung cancer tissues presented significant positive staining for the ASPM protein, with a significantly greater intensity and range of staining." (PMID 40979592, 2025). "RT‒qPCR revealed that the relative expression of ASPM mRNA was significantly upregulated in lung cancer tissues." (PMID 40979592, 2025). "We used two experimental techniques, immunohistochemistry (IHC) and RT‒qPCR, to verify the expression of ASPM in lung cancer tissues at both the protein and RNA levels." (PMID 40979592, 2025). "These functional assays demonstrated that high ASPM expression promoted spindle misorientation in lung cancer cells, which would be expected to negatively affect the equal segregation of chromosomes." (PMID 40873651, 2025). "We utilized these cell models to further investigate the specific role of ASPM in lung cancer cell proliferation and invasion." (PMID 40979592, 2025). "Taken together, these experimental results further confirmed that ASPM plays an indispensable role in the proliferation and invasion of lung cancer cells." (PMID 40979592, 2025). "To further validate the effect of ASPM expression on the osimertinib sensitivity of lung cancer cells, we silenced the ASPM gene in PC-9 and PC-9 ORs to explore the role of ASPM in drug resistance." (PMID 40979592, 2025). "This study mainly explores the relationship between the ASPM expression of lung adenocarcinoma and the development and prognosis of lung cancer." (PMID 31948535, 2020). "Thereby, to explore the potential function of ASPM in the development of lung squamous cell carcinoma, another large type of lung cancer, several assays were all performed." (PMID 32742488, 2020). "The expression of ASPM is incrementally upregulated in primary and metastatic lung cancer, indicating its potential roles in the occurrence and progression of lung cancer." (PMID 33187219, 2020). "ASPM is also reported widely expressed in multiple tumor tissues and involved in the development and progression of several cancers including lung cancer." (PMID 32742488, 2020). "To verify whether ASPM plays an integral role in the proliferation and invasion of relevant cell lines in lung cancer, we selected 3 cell lines: human lung cancer PC-9, PC-9 OR, and LLC." (PMID 40979592, 2025). "Next, we analyzed the Gene Expression Profiling Interactive Analysis (GEPIA) database for ASPM expression in relation to survival and found that patients with lung cancer and high ASPM expression had higher mortality rates than patients with low ASPM expression." (PMID 40873651, 2025). "Our findings suggest that ASPM is a key regulator with an important role in promoting RT resistance in non‐small cell lung cancer, and that suppressing or blocking its expression could be worth exploring as therapy for a variety of RT‐resistant cancers." (PMID 40873651, 2025). "A study believed that ASPM is highly expressed in cancer tissue of LUAD patients and is closely related to the occurrence of lung cancer, with prognosis significance." (PMID 33968130, 2021). "Similarly, in lung cancer, radioresistance-related signatures also predict patient outcomes and immune status, identifying TOP2A, CDH3, ASPM, CENPF, SLC2A1, and PRC1 as potential detection biomarkers for early lung cancer." (PMID 41041339, 2025).
lung carcinoma (continued). "In summary, through WGCNA and differential gene expression analysis, our study generated the significant genes, ASPM, CDCA8, CENP5, CEP55, and PLK1 that may be biomarkers and has potential for treatment in HIV‐infected lung cancer." (PMID 35608130, 2023). "Compared to normal tissues, ASPM and KIF2C expressions were significantly elevated in lung cancer tissues within three datasets (Hou Lung, Selamat Lung, and Okayama Lung) and five datasets (Hou Lung, Landi Lung, Okayama Lung, Stearman Lung, and Su Lung), respectively." (PMID 33187219, 2020). "Suberoylanilide hydroxamic acid significantly enhanced the tumor initiating capacity and the expression of malignant genes such as ASPM in the remaining living ALDH cells, which can suppress the growth of tumor xenografts and decreases the lung cancer stem cell population in vivo." (PMID 31726467, 2019). "Among them, five genes (ASPM, CDCA8, CENPF, CEP55, and PLK1) were present in both three hub gene lists (intersection gene, DEGs, and WCGNA module) suggesting that these five genes may become key genes involved in HIV‐infected lung cancer." (PMID 35608130, 2023). "In addition to our findings on LMO1, we identified five genes (GNG4, NCAPG, SPC25, ASPM and KIF2C) that are expressed at higher levels in lung tumors relative to NATs and are significantly correlated with poor survival of lung cancer patients, suggesting possible oncogenic functions in lung cancer." (PMID 30038707, 2018).
lung adenocarcinoma (11 papers, 2013 to 2025). A carcinoma that arises from the lung and is characterized by the presence of malignant glandular epithelial cells. "In the meantime, we calculated ploidy scores for lung adenocarcinoma samples from The Cancer Genome Atlas dataset and found that high ASPM expression was more likely to be linked with high ploidy scores." (PMID 40873651, 2025). "We found that abnormal spindle‐like microcephaly‐associated protein (ASPM) was highly expressed in RT‐resistant samples and significantly correlated with disease advance in lung adenocarcinoma." (PMID 40873651, 2025). "Previous study indicated that ASPM was involved in the development and progression of lung adenocarcinoma and was associated with poor prognosis." (PMID 32742488, 2020). "Collectively, these findings show that ASPM has similar effects in vivo and in vitro and suggest that ASPM in RT‐resistant cells has a conserved role in the pathogenesis and progression of lung adenocarcinoma by affecting the stability of microtubules." (PMID 40873651, 2025). "ASPM overexpression in lung adenocarcinoma has been correlated with poor prognosis and tumor aggressiveness." (PMID 36661515, 2023). "Previous studies have suggested that ASPM may be a potential target for the treatment of lung adenocarcinoma through screening, also, ASPM gene was frequently altered by missense and nonsense mutations." (PMID 32742488, 2020). "Whether ASPM plays a similar role in lung adenocarcinoma deserves further study." (PMID 32742488, 2020).
pancreatic cancer (9 papers, 2019 to 2024). "ASPM, CCNB1, CDK1, MELK, OAS3, PPTG1 and TOP2A were thought to be significantly associated with shorter overall survival in pancreatic cancer patients." (PMID 36167975, 2022). "ASPM high-expression correlated with poor patient survival was also identified in pancreatic cancer." (PMID 32742488, 2020). "ASPM played a substantial role in Wnt signaling which could predict the outcome and survival of pancreatic cancer, as well as promote hepatocellular progression via autophagy." (PMID 36186452, 2022).
bladder cancer (8 papers, 2019 to 2025). "Overexpression of the ASPM gene is associated with aggressiveness and poor outcome in bladder cancer." (PMID 35515103, 2022). "Bioinformatic analysis based on TCGA and GEO Data found that high expression levels of ASPM are associated with the poor prognosis of patients with bladder cancer." (PMID 33538002, 2021). "Consistent with our research, increased expression of ASPM in bladder cancer patients is associated with poor prognosis." (PMID 32047816, 2020). "Surprisingly, the expression levels of CDC20 and ASPM are associated with the prognosis of patients with bladder cancer." (PMID 32047816, 2020). "Recently, another study reported significant overexpression of ASPM in bladder cancer that was associated with invasive pathological characteristics." (PMID 31828101, 2019). "Overexpression of the ASPM gene is associated with a poor prognosis in bladder cancer." (PMID 35515103, 2022). "The purpose of this study was to assess the critical role that ASPM plays in the development of cancer and determine whether it can be used as a biomarker for bladder cancer." (PMID 32047816, 2020). "We believe that CDC20 and ASPM may affect the development of bladder cancer by affecting TOX molecules." (PMID 32047816, 2020). "In vitro, we interfered with the expression of ASPM and CDC20 and then used the cell counting kit-8 experiment and clone formation experiment to detect the effect on the proliferation of bladder cancer T24 cell line." (PMID 32047816, 2020). "In addition, we interfered with the expression of ASPM and CDC20 in vitro and then used the cell counting kit-8 experiment and clone formation experiment to detect the effect on the proliferation of bladder cancer T24 cell line." (PMID 32047816, 2020). "In addition, the biological role of the ASPM and CDC20 molecules in the development of bladder cancer was confirmed by in vitro experiments." (PMID 32047816, 2020).
lung squamous cell carcinoma (7 papers, 2019 to 2023). "In addition, ASPM is associated with cell cycle progression in pancreatic ductal adenocarcinoma and cell proliferation in lung squamous cell carcinoma." (PMID 33937050, 2021). "Abnormally expressed ASPM induces the progression of lung squamous cell carcinoma through modulating CDK4." (PMID 34987580, 2021). "On this basis, we performed Kaplan-Meier analysis assay to explore the link between ASPM expression and prognosis of patients with lung squamous cell carcinoma." (PMID 32742488, 2020). "Firstly, ASPM expression in tumor tissues of lung squamous cell carcinoma patients who underwent surgical resection was examined by immunohistochemistry assays." (PMID 32742488, 2020). "Taken together, our data provides strong evidence that ASPM promotes lung squamous cell carcinoma proliferation in vitro and in vivo, and indicates its potential role as a LSCC therapeutic target." (PMID 32742488, 2020). "Thus, ASPM could represent a novel therapeutic target to combat lung squamous cell carcinoma." (PMID 32742488, 2020).
ovarian carcinoma (7 papers, 2011 to 2024). A malignant neoplasm originating from the surface ovarian epithelium. "Additionally, ASPM was involved in the progression of ovarian cancer, and associated with the clinical features, such as tumor grade, of ovarian cancer." (PMID 32742488, 2020). "Analysis of the slot blot data for ASPM revealed that there were differences in the ASPM protein levels among the different ovarian cancer cell lines." (PMID 21505456, 2011). "Having established that at both the mRNA and protein levels there were differences in ASPM expression among established ovarian cancer cell lines and the primary cultures, we next investigated the cellular localisation and expression levels of ASPM using immunofluorescence." (PMID 21505456, 2011).
Intellectual disability (5 papers, 2015 to 2022). "Have been noticed in the ASPM mutant, organoids decreased electrical activity and maturation, which confirms the correlation and role of ASPM mutations in congenital mental retardation in patients." (PMID 36518994, 2022). "We identified a novel homozygous variant c.10097_10098delGA, p.(Gly3366Glufs*19) in exon 26 of ASPM gene in family A which presents with moderate intellectual disability, speech impairment, visual abnormalities, seizures, and ptyalism." (PMID 35035405, 2022). "Many of these genes have been previously implicatedwith human phenotypes, including developmental delay (e.g. ASPM, AFF3 and MAPT) and intellectual disability (e.g. NEMF, PI4KA and KANSL1)." (PMID 31757203, 2019). "Of the genetic defects found outside the MD gene panel, seven genetic defects were found in genes present in the intellectual disability gene panel (ARID1B, SCN1A, ASPM, CTNNB, KDM6A, SMARCA4 and SETBP1)." (PMID 25735936, 2015).
liver cancer (5 papers, 2021 to 2024). An epithelial or non-epithelial malignant neoplasm that arises from the liver. "High expression of RRM2, MADAL1, MELK, NCAPG and ASPM were associated with poor OS for liver cancer patients." (PMID 35928445, 2022). "In this article, we show that expression of abnormal spindle‐like microcephaly‐associated protein (ASPM) is up‐regulated in liver cancer samples, and this up‐regulation is significantly associated with tumor aggressiveness and reduced survival times of patients." (PMID 34428354, 2021). "Kaplan–Meier analysis revealed that the expression of ASPM was significantly associated with overall survival of patients with liver cancer (P = 0.004), showing a median survival of >34.0 months in ASPM low‐expression group versus 24.4 months in the ASPM high‐expression group." (PMID 34428354, 2021). "The high protein expression level of ASPM was observed in normal liver tissues, and that in liver cancer tissues was medium." (PMID 35928445, 2022). "Altogether, the results suggest that ASPM exerts its tumor‐promoting function through activating the Wnt/Dvl2/β‐catenin pathway in liver cancer." (PMID 34428354, 2021). "In this study, we revealed that ASPM was highly expressed not only in different histological types of liver cancer but also in different phases of HCC (primary HCC and recurrent HCC), as well as in HCC‐derived cell lines." (PMID 34428354, 2021). "Given the significant correlation between ASPM expression level and malignant clinicopathologic features in liver cancer samples, we hypothesize that ASPM may play a functional role in the tumorigenesis and progression of liver cancer." (PMID 34428354, 2021). "In this work, we found that ASPM is highly expressed, at both mRNA and protein levels, in liver cancer tissues, especially in early recurrent HCC, and up‐regulation of ASPM is significantly related to malignant clinicopathological features and short overall survival in patients with liver cancer." (PMID 34428354, 2021). "Therefore, we conclude that ASPM is a novel oncogene in liver cancer and could serve as a potentially valuable therapeutic target for liver cancer." (PMID 34428354, 2021). "In particular, the expression of ASPM and FANCD2 were significantly upregulated in gallbladder cancer and liver cancer tissue samples versus their respective controls." (PMID 38903178, 2024). "The expression of ASPM mRNA was significantly up‐regulated in liver cancer tissues compared with that in adjacent nontumor tissues (P < 0.0001)." (PMID 34428354, 2021).
malignant glioma (4 papers, 2010 to 2022). A grade III or grade IV glioma arising from the central nervous system. "In malignant gliomas, ASPM expression levels were positively associated with tumor grades and increased in recurrent tumors." (PMID 31106147, 2019). "ASPM (Abnormal Spindle-like Microcephaly associated) over-expression was recently implicated in the development of malignant gliomas." (PMID 20142996, 2010). "ASPM (abnormal spindle-like microcephaly-associated) has been implicated in a cell-fate determination of neuronal progenitor cells and in the development of malignant gliomas." (PMID 34359798, 2021). "Recent evidence suggests that ASPM is also overexpressed in malignant gliomas and that its knockdown inhibits tumor proliferation." (PMID 20142996, 2010). "Aberrant expression of ASPM facilitated the tumorigenesis of malignant gliomas." (PMID 35387319, 2022). "However, the dramatic inhibition of gliomasphere proliferation obtained with shRNA-mediated ASPM knockdown highlights the potential importance of this gene in malignant gliomas." (PMID 20142996, 2010).
brain tumors (3 papers, 2021 to 2024). "With regard to pediatric brain tumors, ASPM was found highly expressed in MB samples, compared to normal tissue, and its levels correlated with worse overall survival of MB patients." (PMID 34663805, 2021). "Besides PRUNE_1, the other five genes (i.e., KIF11, KIF14, ASPM, CDK6, and ATR) have been reported as mutated in hereditary MCPH and overexpressed in primary brain tumors (e.g., MB)." (PMID 34745995, 2021). "In conclusion, inhibition of KNL1, CENPE, ASPM, CITK, and KIF14 may mimic the effects of MTAs on cell division but could work with particular effectiveness on brain tumor cells, underscoring the importance of developing specific inhibitors and test them in clinical trials." (PMID 34663805, 2021).
pancreatic adenocarcinoma (3 papers, 2020 to 2024). "Similar effects of ASPM have been reported in pancreatic adenocarcinoma and other malignancies, indicating its role in inducing cancer cell stemness and accelerating tumor progression." (PMID 39594769, 2024). "The results showed that ASPM is overexpressed in most human cancers, such as GBM, oesophageal carcinoma (ESCA), liver hepatocellular carcinoma (LIHC) and pancreatic adenocarcinoma (PAAD)." (PMID 31905171, 2020).
pancreatic ductal adenocarcinoma (3 papers, 2021 to 2025). An infiltrating adenocarcinoma that arises from the epithelial cells of the pancreas. "ASPM also promotes Wnt pathway activity and cancer stemness by positively regulating Dvl-2 and β-catenin in pancreatic ductal adenocarcinoma." (PMID 35387319, 2022).
psoriasis (3 papers, 2022 to 2024). An autoimmune condition characterized by red, well-delineated plaques with silvery scales that are usually on the extensor surfaces and scalp. "We found that core genes (TOP2A, MELK) were highly expressed in psoriasis samples and lowly expressed in normal tissue samples, while DEPDC1B, CCNA2, DLGAP5, NUF2, ASPM were lowly expressed in psoriasis samples." (PMID 38382096, 2024). "The gene expression heatmap showed high expression of core genes (TOP2A, MELK) in psoriasis samples, while DEPDC1B, CCNA2, DLGAP5, NUF2, ASPM were lowly expressed in psoriasis samples." (PMID 38382096, 2024).
small cell lung carcinoma (3 papers, 2016 to 2025). Small cell lung cancer (SCLC) is a highly aggressive malignant neoplasm, accounting for 10-15% of lung cancer cases, characterized byrapid growth, and early metastasis. "The skin tumor could not be ascribed to skin cutaneous melanoma but was more likely to arise from small cell lung cancer with 65 common mutated genes, such as CORIN and ASPM." (PMID 27442652, 2016).
breast tumors (2 papers, 2013 to 2023). "The expression levels and subcellular localization of the CCNB2, ASPM, CDCA7, KIAA0101, and SLC27A2 proteins were measured using immunohistochemistry (IHC) on a panel of 80 primary invasive breast tumors." (PMID 23282137, 2013).
cervical cancer (2 papers, 2021 to 2023). A primary or metastatic malignant neoplasm involving the cervix. "Although MAD2L1, TOP2A, AURKA, and ASPM were reported in various research findings, they may play a remarkable role in the survival of cervical cancer." (PMID 36723760, 2023).
Cirrhosis (2 papers, 2020 to 2021). A chronic disorder of the liver in which liver tissue becomes scarred and is partially replaced by regenerative nodules and fibrotic tissue resulting in loss of liver function. "ASPM is associated with the development of HCV-related cirrhosis via the regulation of tumor-associated phosphorylation." (PMID 33505422, 2020).
colon cancer (2 papers, 2023 to 2024). "Among these genes, ASPM was confirmed to promote colon cancer progression." (PMID 39830210, 2024).